CASP1 (caspase 1)
Diseases named in the same sentence as CASP1 in open-access papers (continued):
Sharing a sentence is not in itself a finding about the gene and the disease.
disseminated candidiasis (5 papers, 2010 to 2021). Systemic candidiasis occurs when Candida yeast enters the bloodstream and may spread (becoming disseminated candidiasis) to other organs, including the central nervous system, kidneys, liver, bones, muscles, joints, spleen, or eyes. "To determine if caspase-1-dependent cell death was occurring during disseminated candidiasis in mammals, we infected both wild-type (WT) and caspase-1-deficient mice with C. albicans strain SC5314 by tail vein injection." (PMID 30065091, 2018). "We have observed caspase-1-dependent cell death in a murine model of disseminated candidiasis." (PMID 30065091, 2018). "This indicates that caspase-1 and ASC have strongly protective antifungal capacities through controlling Th1 and Th17 responses during disseminated candidiasis, due to activation of the NLRP3/ASC/caspase-1 pyroptosis pathway." (PMID 34908455, 2021). "For instance, host resistance to disseminated candidiasis is provided by neutrophil-derived proteinase 3 activation of IL-1β and not caspase-1 activation." (PMID 30583612, 2018). "It is the neutrophils that form the backbone of the inflammatory infiltrates during disseminated candidiasis, and this explains the dependency of host defense against Candida on IL-1β, most likely activated by neutrophil-derived PR3, rather than caspase-1." (PMID 20195505, 2010).
dry eye (5 papers, 2015 to 2023). "Zheng and colleagues found NLRP3, caspase-1, and IL-1b increased in impression cytology samples from patients with dry eye, as well as in cultured cells exposed to hyperosmolar medium." (PMID 36902183, 2023). "Higher levels of inflammasome can in turn activate caspase-1 and the secretion of IL-1β and IL-18, which then induce the inflammatory damage of dry eye." (PMID 25962072, 2015). "Increased levels of caspase-1 have been detected in tears of dry eye patients." (PMID 37036417, 2023). "A recent study reported that reactive oxygen species could trigger NLRP3 inflammasome and lead to caspase-1 auto-activation and maturation of proinflammatory cytokines IL-1β in dry eye murine models." (PMID 25962072, 2015). "A desiccating stress-induced dry eye mouse model with elevated levels of NLRP3 inflammasome, ASC, and CASP1 has been detected together with mature IL-1β and IL-18." (PMID 36614174, 2023). "In the current study, we found that mRNA and protein expressions of NLRP3 inflammasome were upregulated in human dry eyes, especially in SSDE; the downstream inflammatory factors caspase-1, IL-1β, and IL-18 were also elevated in dry eye patients." (PMID 25962072, 2015). "In summary, based on tear samples and conjunctival impression cytology specimens of dry eye patients, we found that the expressions of NLRP3 inflammasome and its downstream inflammatory factors-caspase-1, IL-1β and IL-18 are upregulated in dry eye patients, especially in SSDE." (PMID 25962072, 2015).
glaucoma (5 papers, 2021 to 2025). Increased pressure in the eyeball due to obstruction of the outflow of aqueous humor. "Notably, IHC showed that cGAS, STING, GSDMD, and Caspase-1 were significantly upregulated in the retinas of glaucoma patients." (PMID 37726272, 2023). "Finally, mechanistic similarities between acute spOHT and chronic OHT-induced glaucoma, including the inflammasome/CASP1-dependent RGC dysfunction and death, suggest that spOHT can be instrumental in studies of the earliest pathophysiological events in the OHT-challenged retina." (PMID 37998361, 2023). "More importantly, the proteins regulated by GFAP mAb formed a closely connected protein interaction network with the characteristic proteins of glaucoma, in which GFAP and Caspase-1 were revealed as the central nodes." (PMID 40528237, 2025). "In a mouse model for acute elevated IOP-induced glaucoma, NLRP1, NLRP3, ASC, and caspase-1 levels were rapidly upregulated in the retina after ischemic injury." (PMID 35047535, 2021). "This indicates that GFAP mAb may modulate the pathological protein network of glaucoma, particularly through the key regulators GFAP and Caspase-1." (PMID 40528237, 2025). "However, recent studies have implicated inflammasomes, caspase-1, and GSDMD in acute and chronic models of glaucoma, suggesting that apoptosis is not the only form of cell death involved in glaucomatous RGC loss." (PMID 35047535, 2021).
gram-negative bacterial infections (5 papers, 2016 to 2022). Infections caused by bacteria that show up as pink (negative) when treated by the gram-staining method. "Research shows that caspase-11 is the upstream regulator of caspase-1 at the TIR-domain-containing adaptor-inducing interferon-β/IFN/caspase-11 axis in all Gram-negative bacterial infections." (PMID 33467535, 2021). "Caspase-11 regulates the activation of caspase-1 in the non-canonical inflammasome during Gram-negative bacterial infection." (PMID 35345462, 2022). "In contrast to caspase-1, caspase-4, -5 and -11 act mainly in response to lipopolysaccharide coming from Gram-negative bacterial infection with the non-canonical inflammasome pathway." (PMID 33467535, 2021).
Granuloma (5 papers, 2020 to 2025). A compact, organized collection of mature mononuclear phagocytes, which may be but is not necessarily accompanied by accessory features such as necrosis. "By day 14, granulomas were considerably enlarged and almost replaced the liver parenchyma in Casp-1-/- and Nlrp3-/- mice when compared to those at 7 dpi, but liver sections from WT mice exhibited a smaller number of granulomas." (PMID 34912336, 2021). "Histological studies of liver sections from WT, Casp-1-/- and Nlrp3-/- mice at 7 dpi showed a great number of granulomas." (PMID 34912336, 2021). "It is clear that the inflammasome pathway is important for Schistosoma-induced liver pathology, once we have observed granuloma reduction and lower collagen deposition in Casp-1–/–, Gsdmd–/–, and IL-1R–/– mice when compared to WT." (PMID 32431709, 2020). "Many other granuloma models have had contrasting conclusions as to whether caspase-1/11 and gasdermin D contributed to granuloma biology." (PMID 37865673, 2023). "Finally, it was further demonstrated that the onset of hepatic granuloma and collagen deposition were also compromised in Caspase-1–/–, IL-1R–/– and Gsdmd–/– mice." (PMID 32431709, 2020). "Then, the soluble antigens (SEA) released by the eggs can cause granuloma inflammation, inducing the immune system to shift from Th1 to Th2 response and continuously stimulating HSCs to produce NLRP3 inflammatory body activation of intracellular caspase-1 and TGF-β expression." (PMID 41451374, 2025).
hematoma (5 papers, 2022 to 2026). A hematoma is a collection of blood from a vascular structure into an extravascular space. "Effects of NR on (a) NLRP3, (b) ASC, and (c) Caspase-1 protein levels in the peri-hematoma tissue 24 h following ICH." (PMID 38981960, 2025). "Immunofluorescence staining results showed that the amount of Caspase-1-positive microglia in the peri-hematoma tissue was increased at 24 h after ICH." (PMID 35154128, 2022). "NLRP3, ASC, and Caspase-1 levels in the peri-hematoma tissues were measured to assess whether NR plays a protective role by inhibiting inflammasome activation." (PMID 38981960, 2025). "However, Didymin treatment decreased the amount of Caspase-1-positive microglia in the peri-hematoma tissue at 24 h after ICH." (PMID 35154128, 2022). "To further explore the activation of the NLRP3/ASC/ caspase-1 pathway in brain tissues after ICH, we detected the protein samples from brain tissues around the hematoma by western blotting analysis." (PMID 38645501, 2024). "During the initial compression by hematoma, mechanical strain-induced P2X7 receptors can activate NLRP3 inflammasomes and caspase-1." (PMID 35370546, 2022). "For hemorrhagic stroke, NLRP3 upregulation, caspase-1 activation, and IL-1β release occur as early as 3 h post-ICH and intensify gradually in the area around the hematoma from 1 to 5 days." (PMID 35370546, 2022).
Immunodeficiency (5 papers, 2015 to 2023). Failure of the immune system to protect the body adequately from infection, due to the absence or insufficiency of some component process or substance. "CASP1 mediated autophagy to regulate mitochondrial dysfunction can also effectively control the immune system disorders of inflammatory immune diseases." (PMID 33777735, 2021). "Humans who possess genetic variants of caspase-1 that display low enzymatic activity do not suffer from immunodeficiency." (PMID 32907600, 2020). "MHV68 latency also protected IL-6, Caspase-1 and Caspase-1;Caspase-11 deficient mice from Listeria-induced lethality, indicating that the ability of latent infection to complement a genetic immunodeficiency is not restricted to mutation of Hoil-1." (PMID 25599590, 2015).
kidney inflammation (5 papers, 2011 to 2025). "Again, heterologous anti-GBM nephritis displayed an identical histomorphological and functional phenotype in caspase-1-deficient mice as compared to their respective wildtype controls as assessed by scoring glomerular injury, urinary albumine/creatinine ratio and other renal function parameters." (PMID 22046355, 2011). "In summary, heterologous anti-GBM nephritis develops independently of the NLRP3-ASC-caspase-1 axis likely due to an inability for glomerular cells to induce and to secrete IL-1β." (PMID 22046355, 2011). "Concurrently, it inhibited the mRNA expression of renal inflammatory cytokines via the inhibition of NLRP3/Caspase-1 and TLR4/MyD88/NF-κB signaling pathways, thereby alleviating the HUA-induced kidney inflammation." (PMID 41300001, 2025). "Accumulating studies have shown that the NLRP3 inflammasome, which is composed of the NLRP3 protein, caspase-1, and ASC, plays a pivotal role in DKD kidney inflammation, especially in podocytes, endothelial cells, and renal tubular epithelial cells." (PMID 34504642, 2021). "The intrarenal expression of NLRP3, ASC, and caspase-1 suggests that they might be involved in the secretion of IL-1β and inflammation during anti-GBM nephritis." (PMID 22046355, 2011). "Direct evidence comes from LPS-enhanced heterologous anti-GBM nephritis in rats which were found to be partially protected by anti-IL-1β antibody treatment, but a contribution of NLRP3, ASC, and caspase-1 for intrinsic glomerular inflammation is still speculative." (PMID 22046355, 2011).
Legionella infection (5 papers, 2011 to 2025). "To better understand the role of caspase-11 and caspase-1 in vesicular trafficking, we focused on physiological doses of Legionella infection and early trafficking events that mimic early infection stages." (PMID 26686473, 2015). "To determine if caspase-1 is required for the dephosphorylation of cofilin in response to Legionella infection by halting the activity of kinases or promoting the activity of phosphatases that converge on cofilin, we first assessed Rac1 and Cdc42 activation." (PMID 26686473, 2015). "In addition, these results show that caspase-11 and caspase-1 are both necessary to increase the F/G actin ratio during Legionella infection but are dispensable for the trafficking of vacuoles containing non-pathogenic bacteria." (PMID 26686473, 2015). "Interestingly, caspase-11 is required for the phosphorylation of cofilin, while caspase-1 is essential for its dephosphorylation upon Legionella infection." (PMID 26686473, 2015). "Pyroptosis is distinct death mode that may be induced by Shigella, Salmonella, Francisella or Legionella infection in a strictly caspase-1-dependent manner." (PMID 21483832, 2011). "In addition, we performed Kyoto Encyclopedia of Genes and Genomes (KEGG) analysis, confirmed that co-expression gene of CASP1 enrichment in leishmaniasis, lysosome, legionellosis, endocytosis, cytokine receptor interaction, NOD-like, and B cell receptor signaling pathway." (PMID 33999861, 2021). "In animal models of Legionella infection, it has indeed been proven that the NLR family CARD domain containing 4 (NLRC4) inflammasome drives pyroptosis through caspase-1 activation and IL-18 release." (PMID 37965258, 2023). "Casp1/11−/− DCs did not undergo cell death until 4 h following T4SS+Legionella infection, whereas WT DCs exhibited rapid cell death within 1 h post-infection." (PMID 40530878, 2025). "On the other hand, dephosphorylation (activation) of the Slingshot phosphatase does not occur in cells lacking caspase-1 but proceeds efficiently in WT and Casp-11−/− macrophages during Legionella infection." (PMID 26686473, 2015). "Nlrp3−/− or Casp1−/− BMDCs infected with T4SS+Legionella exhibited WT levels of cell death, indicating that while NLRP3 and caspase-1 drive IL-1β release, they are not required for DC death during Legionella infection." (PMID 40530878, 2025).
mastitis (5 papers, 2013 to 2026). Inflammation of breast tissue during lactation or postpartum due to an obstructed duct or infection. "Pathway enrichment analysis indicated that NLRP3, caspase-1 (CASP1), and GSDMD were enriched in the NOD-like receptor signaling pathway and were closely associated with mastitis." (PMID 41897529, 2026). "NLRP3 inflammasome activation in subclinical mastitis and after LTA stimulation in MAC-T cells and murine mammary glands was confirmed in the present study by the upregulation of NLRP3, ASC, cleaved-caspase-1 and IL-1β." (PMID 39765775, 2024). "According to Western blotting results, the mammary gland with subclinical bovine mastitis exhibited obviously increased protein expressions concerning ASC, cleaved-caspase-1, NLRP3, and IL-1β compared with the healthy ones." (PMID 39765775, 2024). "In addition to TNFa and IL-1b, CASP1 and NFKB1 were found to be up-regulated in our study suggesting that TREM1 signaling may likely provide the link between TLR2- and NLR-mediated signal transduction in cytokine-induced inflammation during the initiation of host defense such as in mastitis." (PMID 24341851, 2013).
pericarditis (5 papers, 2022 to 2025). An inflammatory process affecting the pericardium. "Compared with those in the controls, the expression levels of NLRP3 and caspase-1 were notably elevated in the pericarditis patients, highlighting the key elements of pericarditis development and confirming the theory of medication." (PMID 40079000, 2025). "The expression of NLRP3 and caspase-1 were also observed significantly upregulated in pericarditis cases vs. controls, which echoed the hypothesis from pharmaceutical treatments, emphasizing the essence of the development in pericarditis." (PMID 36204568, 2022). "Confirming its involvement in pericarditis, Mauro’s group reported the presence of NLRP3, ASC and caspase-1 expression in pericardial biopsies from pericarditis patients." (PMID 41272654, 2025).
pneumococcal meningitis (5 papers, 2013 to 2024). An acute purulent infection of the meninges and subarachnoid space caused by Streptococcus pneumoniae, most prevalent in children and adults over the age of 60. "Moreover, mice deficient of caspase-1 displayed less severe inflammation, decreased brain water content and improved clinical score in a pneumococcal meningitis model." (PMID 23902681, 2013). "Conversely, treatment of caspase-1-deficient mice with LPS injection resulted in survival advantage compared to WT mice, and an improved clinical status was was observed in caspase-1-deficient mice with Pneumococcal meningitis and Pseudomonas aeruginosa corneal infection." (PMID 38824481, 2024). "Caspase-1 activation and subsequent cytokine maturation and production were also induced in the mouse model of pneumococcal meningitis." (PMID 26683708, 2015). "Collectively, our results demonstrate that S. pneumoniae, especially pneumolysin, induces the activation of caspase-1 and the release of IL-1β in murine pneumococcal meningitis." (PMID 26683708, 2015). "Second, IL-1β, which is activated by caspase-1, has been shown to be elevated in the CSF of children with pneumococcal meningitis and correlates with disease severity, a finding that also has been observed in various animal models." (PMID 23902681, 2013).
pterygium (5 papers, 2018 to 2024). A wedge-shaped fibrovascular lesion arising from the bulbar conjunctiva and extending to the cornea. "Activation of the NLRP3/caspase-1 pathway may be a cause of angiogenesis andfibroblast proliferation, which could induce pterygium recurrence." (PMID 32490975, 2020). "Based on the results, we considered the possibility that MMC suppresses the activation of the NLRP3/Caspase-1 pathway to weaken neovascularization and fibroblast proliferation in pterygium." (PMID 31827916, 2019). "Further results demonstrated that MMC injection can significantly inhibit the activation of the NLRP3/Caspase-1 pathway in pterygium tissues and thus decrease the expression of IL-1β and IL-18." (PMID 31827916, 2019). "In pterygium, theNLRP3/caspase-1 pathway may be abnormally activated, accompanied by aberrant expressionof IL-18 and IL-1β." (PMID 32490975, 2020). "Therefore, MMC injection can attenuate the activation of the NLRP3/Caspase-1 pathway, thus inhibiting fibroblast proliferation and vascular hyperplasia and reducing the rate of pterygium recurrence." (PMID 31827916, 2019). "The expression of nod-like receptor pyrins-3 (NLRP3), caspase-1, IL-18, and IL-1β was analyzed in 60 human pterygium tissues and 60 human conjunctival epithelium tissues using real-time quantitative polymerase chain reaction (qRT-PCR) and Western blot analysis." (PMID 29724886, 2018). "The protein levels of these factors were highly expressed in pterygium samples compared with normal conjunctiva samples with statistical difference (NLRP3, caspase-1, and IL-1β: P<0.05)." (PMID 29724886, 2018). "Another 30 pterygium samples and 30 normal conjunctiva samples were detected for NLRP3, caspase-1, pro-IL-1β, and IL-1β protein level with Western blot analysis." (PMID 29724886, 2018). "Thirty pterygium samples and thirty normal conjunctiva samples were collected and analyzed for NLRP3, caspase-1, IL-18, and IL-1β mRNA expression using qRT-PCR." (PMID 29724886, 2018). "The mRNA of these factors was highly expressed in pterygium samples with statistical difference (NLRP3: P<0.001; caspase-1: P<0.001; IL-1β: P<0.05; IL-18: P<0.01)." (PMID 29724886, 2018). "More importantly, our findings reveal that MMC reduces the recurrence rate of pterygium by suppressing angiogenesis and fibroblast proliferation via inhibiting NLRP3/Caspase-1 pathway activation and the expression of inflammatory factors such as TGF-β1, VEGF, IL-6." (PMID 31827916, 2019). "For instance, CASP1 could participate in pyroptosis through activated IL1B and IL18, and FASLG could be involved in pterygium fibroblasts, suggesting that they might play a role in pterygium pathogenesis." (PMID 38732006, 2024).